RGS7 (regulator of G protein signaling 7)
Description:
GTPase activator component of the RGS7-GNB5 complex that regulates G protein-coupled receptor signaling cascades. The RGS7-GNB5 complex acts as an inhibitor signal transduction by promoting the GTPase activity of G protein alpha subunits, such as GNAO1, thereby driving them into their inactive GDP-bound form. May play a role in synaptic vesicle exocytosis (Probable). Glycine-dependent regulation of the RGS7-GNB5 complex by GPR158 affects mood and cognition via its ability to regulate neuronal excitability in L2/L3 pyramidal neurons of the prefrontal cortex (By similarity). Modulates the activity of potassium channels that are activated by GNAO1 in response to muscarinic acetylcholine receptor M2/CHRM2 signaling.
Tractability: Small molecule: a structure with a bound ligand is known. Antibody: UniProt places it where antibodies can reach, with high confidence; its Gene Ontology location is reachable by antibodies, with high confidence. PROTAC: UniProt records ubiquitination sites on it; its protein half-life has been measured.
Gene: Protein-coding gene on chromosome 1 (240,767,636 to 241,357,374, reverse strand). Ensembl gene ENSG00000182901.
Subcellular location: Cytoplasm, cytosol; Cytoplasm; Cell membrane; Membrane
Subcellular location (Human Protein Atlas): Cytosol; Mitochondria
Pathways (Reactome):
Metabolism of proteins: Cooperation of PDCL (PhLP1) and TRiC/CCT in G-protein beta folding
Signal Transduction: G alpha (i) signalling events
Gene Ontology:
Molecular function: G-protein alpha-subunit binding; G-protein beta-subunit binding; GTPase activator activity; GTPase activity
Biological process: G protein-coupled receptor signaling pathway; negative regulation of G protein-coupled receptor signaling pathway; positive regulation of GTPase activity; intracellular signal transduction; regulation of G protein-coupled receptor signaling pathway; regulation of postsynaptic membrane potential
Cellular component: cytoplasm; cytosol; membrane; plasma membrane; neuron projection; cell tip; dendrite; dendrite terminus; glutamatergic synapse; nucleus; postsynaptic membrane; presynapse; presynaptic membrane
Genetic constraint (gnomAD): Loss-of-function variants: 15 observed, 48.89 expected, observed/expected ratio (o/e) 0.31, 90% interval 0.2 to 0.47. The upper end of that interval is the gene's LOEUF score, 0.47, which puts it in group 2 of 6, group 1 being the genes least tolerant of losing a copy. Missense variants: 239 observed, 416.93 expected, observed/expected ratio (o/e) 0.57, 90% interval 0.51 to 0.64. Synonymous variants: 138 observed, 149.26 expected, observed/expected ratio (o/e) 0.92, 90% interval 0.8 to 1.07.
Homologues: Orthologues: dog RGS7 (99% identical), pig RGS7 (98% identical), chimpanzee RGS7 (96% identical), macaque RGS7 (96% identical), guinea pig RGS7 (95% identical), rat Rgs7 (95% identical), mouse Rgs7 (91% identical), rabbit RGS7 (88% identical), zebrafish rgs7a (82% identical), zebrafish rgs7b (70% identical). Paralogues in human: RGS6 (70% identical), RGS9 (37% identical), RGS11 (35% identical), RGS3 (20% identical), RGS12 (19% identical), RGSL1 (19% identical), RGS22 (18% identical), RGS5 (13% identical), RGS17 (12% identical), RGS1 (12% identical), RGS20 (12% identical), RGS14 (12% identical), and 11 more.
Diseases named in the same sentence as RGS7 in open-access papers:
RGS7 is named in the same sentence as 36 diseases in open-access papers, as found by Europe PMC text mining. Sharing a sentence is not in itself a finding about the gene and the disease. The quoted sentences say what the papers report.
Obesity (5 papers, 2011 to 2017). Accumulation of substantial excess body fat. "SNPs from genes associated with alcohol dependence (ESR1) and obesity traits (RGS7, NRG3 and ESR1) were observed among Western reported dietary pattern score-associated SNPs." (PMID 28644415, 2017). "A GWAS of childhood obesity in Hispanic populations showed nominal association of RGS7 with fasting plasma vitamin B12, a marker of obesity." (PMID 27111224, 2016). "Third, RGS7 is part of a QTL hotspot in the syntenic region of mouse chromosome 1 implicated in obesity and behavioral phenotypes; it is quite possible that a similar body composition QTL hotspot exist on human chromosome 1q43." (PMID 27111224, 2016). "Our early linkage scan for obesity loci in the Quebec Family Study has highlighted RGS7 as a potential candidate gene for body fat in individuals of European descent." (PMID 23555580, 2013). "Human genetic studies have linked variations in two other R7 RGS proteins, RGS6 and RGS7 to obesity." (PMID 22132185, 2011). "Of note, although variants on chromosome 1q43 have been associated with body composition and obesity-associated metabolic traits, to our knowledge specific associations with RGS7 variants have not been reported to date." (PMID 27111224, 2016).
melanoma (4 papers, 2018 to 2023). A malignant, usually aggressive tumor composed of atypical, neoplastic melanocytes. "Both of these effects are expected to contribute to loss of function of RGS7 resulting in increased anchorage-independent growth, migration and invasion of melanoma cells." (PMID 29330521, 2018). "Our analysis detected 67 non-synonymous RGS7 mutations in melanoma samples, 65% of which were predicted by SIFT analysis to be deleterious." (PMID 29330521, 2018). "In agreement with the tumor-suppressor role of RGS7, overexpression of wild-type RGS7 in melanoma cell lines harboring the RGS7 mutation (R44C: 53 T and 67 T) led to reduced cell migration and invasion." (PMID 29330521, 2018). "Analysis of 501 melanoma exomes revealed RGS7, which encodes a GTPase-accelerating protein (GAP), to be a tumor-suppressor gene." (PMID 29330521, 2018). "Curiously, a pathogenic mutation (R44C) in the β-hairpin of RGS7 that causes melanoma reduces the stability of RGS7 and its catalytic activity, further supporting the importance of conformational transitions in this region in regulating RGS7 function." (PMID 30540250, 2018). "RGS7, initially localized as a tumour suppressor, is unstable in melanoma and prone to recurrent mutations, thus promoting the migration and invasion of melanoma cells, which may be related to the diminished activity of RGS7 in catalysing Gα-GTP hydrolysis and the instability of the protein itself." (PMID 37924113, 2023). "To validate the extent to which RGS7 is expressed in human melanomas, we performed RGS7 immunohistochemistry (IHC) on a set of melanoma patient tissues." (PMID 29330521, 2018). "The reduced activity of the R44C mutant promotes melanoma cell migration and invasion, providing a molecular mechanism by which RGS7 suppresses melanoma tumorigenesis." (PMID 29330521, 2018). "Our findings identify RGS7 as a novel melanoma driver and point to the clinical relevance of using strategies to stabilize the protein and, thereby, restore its function." (PMID 29330521, 2018). "We also found RGS7 to alter melanoma cell migration and invasion capabilities." (PMID 29330521, 2018). "We tested the expression of RGS7 in normal human adult melanocytes and melanoma cells." (PMID 29330521, 2018).
depression (3 papers, 2021 to 2023). "The interaction of GPR158 with RGS7 in the PFC of mice is a key mechanism leading to behavioral abnormalities in stress-induced depression." (PMID 36979415, 2023). "Together, these findings begin to demonstrate the specific contribution of Rgs7 acting in the striatum toward depression as it relates to stress-induced reinstatement of drug use." (PMID 33402347, 2021). "In summary, our data demonstrates that Rgs7 plays a prominent role in depression and the regulation of stress-induced reinstatement of cocaine CPP." (PMID 33402347, 2021). "Mice with a global knock-out of Rgs7 exhibit marked antidepressant-like behaviors and a resilience to chronic stress-induced depression." (PMID 33402347, 2021). "The current study demonstrates the contribution of striatal Rgs7 toward depression-related behaviors and their relevance to substance abuse." (PMID 33402347, 2021). "In this study we explore the role of striatal Rgs7 in depression related phenotypes and its relevance to regulating reward-related behaviors." (PMID 33402347, 2021). "In this study, we report a key role of Rgs7 in the striatum toward depression and reward-related behaviors, while addressing the effects of stress on these behavioral outcomes." (PMID 33402347, 2021). "In addition to Rgs7 being a mediator of stress reinstatement, it also prevents stress-induced depression." (PMID 33402347, 2021). "Thus, loss of Rgs7, but not Rgs9, in the striatum selectively affects depression-related behaviors." (PMID 33402347, 2021).
breast carcinoma (2 papers, 2015 to 2024). "Perhaps of relevance, data mining results obtained in the current study indicate that RGS7 is co-expressed with GPR158 in breast cancer along with many NE markers." (PMID 25693195, 2015).
uterine fibroid (2 papers, 2015 to 2016). "In the present study, we re-assessed the association of BMI with a dense set of chromosome 1q43 SNPs in a sample of 916 women enrolled in the NIEHS uterine fibroid study and report peak of associations in RGS7 in race-stratified analyses and in meta-analysis." (PMID 27111224, 2016).
campomelic dysplasia (1 paper, 2016). "These included regulator of G-protein signaling 4 (RGS4) and 7 (RGS7), which were both upregulated by CCG-1423, and CTGF (connective tissue growth factor), and SOX9 (sex determining region Y-box 9, also referred to as campomelic dysplasia, autosomal sex reversal) which were down-regulated." (PMID 27600078, 2016).
cerebral atherosclerosis (1 paper, 2023). Atherosclerosis of the cerebral vasculature. "The cerebral atherosclerosis-related gene PITX2, RGS7, NKX2-5, NKX2-5, and ZFHX3 are involved in AIS." (PMID 37265472, 2023).
cervical cancer (1 paper, 2021). A primary or metastatic malignant neoplasm involving the cervix. "They identified 6 genes as the best candidate methylated biomarkers of cervical cancer progression (RGS7, LHX8, ST6GALNAC5, TBX20, KCNA3 and ZSCAN18)." (PMID 34882728, 2021).
Down syndrome (1 paper, 2014). "Similar to Down syndrome mouse models, Rgs7−/− mice also exhibited augmented GABABR-GIRK signaling." (PMID 24755289, 2014).
endophthalmitis (1 paper, 2021). An infectious process affecting the internal structures of the eye. "Genes known to have a role in G-Protein-coupled receptor pathway were found to be negatively regulated in MDR-PA endophthalmitis and included Rgs7 and Gprasp2." (PMID 35046947, 2021).
esophageal cancer (1 paper, 2020). A primary or metastatic malignant neoplasm involving the esophagus. "The results showed that EPHA5, LOC100506136, RGS7, THBS4, SCGB1A1, and DPEP1 were dysregulated between esophageal cancer and normal control in GSE13898 validation dataset (all, P<0.05)." (PMID 32068233, 2020).
metastatic tumours (1 paper, 2020). "Other mutations included KDM5C (1/6, OVA_013), FLNA (1/6, OVA_378), RGS7 (1/6, OVA_047) and SPRY2 (1/6, OVA_365), which were also clonal in both primary and metastatic tumours." (PMID 32099096, 2020).
Micro syndrome (1 paper, 2022). "But interestingly, FMN2 and RGS7 deletion was discovered in Warburg–Micro Syndrome patients." (PMID 36192753, 2022).
myeloma (1 paper, 2022). "In agreement with the gene model, compared with bortezomib-sensitive myeloma cell lines (negative control), there was an increase in mRNA expression of SCN9A, RGS7, NTF3, HSPB8, and ZBED1 and a decrease in CCND1, COBLL1, EGR1, OCLN, and ZBED1 mRNA expression of bortezomib-resistant cell lines." (PMID 36467498, 2022).
prostate carcinoma (1 paper, 2016). A carcinoma that arises from epithelial cells of the prostate gland. "In order to confirm the microarray results, we tested by qRT-PCR the effect of CCG-1423 on levels of RGS4, RGS7, CTGF, and SOX9 mRNA in PC-3 prostate cancer cells." (PMID 27600078, 2016). "In order to better understand the timing of CCG-1423-regulated gene expression, we studied the effect of CCG-1423 on RGS4, RGS7, CTGF, and SOX9 gene expression in PC-3 prostate cancer cells from 1 to 24 h." (PMID 27600078, 2016).
tumor (9 papers, 2013 to 2024). "Examination of publically available databases revealed that RGS7 is also mutated in several other tumor types." (PMID 29330521, 2018). "Five genes demonstrated complete loss or downregulation of expression in at least 20% of RCC tumours (GCM2 (80% of RCC), RGS7 (46.7%), TMEM74 (46.7%), NEFM (20%) and AEBP1 (20%))." (PMID 24034811, 2013). "Given that previous studies reported that reduced GAP activity on Gαo increases cell migration and invasion, we hypothesized that RGS7 functions as a tumor suppressor." (PMID 29330521, 2018). "By mutating position 56 in the R44C mutant from valine to cysteine, thereby enabling the formation of a disulfide bridge between the two mutated positions, we slightly increased the catalytic activity and reinstated protein stability, leading to the rescue of RGS7′s function as a tumor suppressor." (PMID 29330521, 2018). "Thus, with subsequent investigation two candidate genes were found to be methylated in more than 25% of our series and in the TCGA methylation dataset for 199 RCC samples: RGS7 (25.6% and 35.2% of tumours respectively) and NEFM in (25.6% and 30.2%)." (PMID 24034811, 2013).
cancer (8 papers, 2011 to 2025). A tumor composed of atypical neoplastic, often pleomorphic cells that invade other tissues. "While the relevance of FH, EXO1, MAP1LC3C and PLD5 functions to the development of cancer is plausible, that of the associated RGS7 is intriguing and deserves comments." (PMID 23555580, 2013). "Likewise, RGS7 rs2502448 was independently associated with the risk of cancer recurrence in the overall cohort (TT vs. CC/CT; aHR = 2.35; 95%CI, 1.20–4.61; P = 0.013) and among male patients (TT vs. CC/CT; aHR = 4.67; 95%CI, 2.00–10.88; P < 0.001)." (PMID 40425987, 2025). "Here, we report a crystal structure and dynamics analyses of the multisubunit complex of RGS7, a major regulator of neuronal signaling with key roles in controlling a number of drug target GPCRs and links to neuropsychiatric disease, metabolism, and cancer." (PMID 30540250, 2018). "RGS7-mediated suppression of Gαo signaling could reduce cancer progression dependent upon Gαo signaling pathways." (PMID 27600078, 2016). "Given these roles, perhaps not surprisingly, the RGS7 complex has been found to play a critical role in vision, learning and memory, drug addiction, insulin production, and cancer progression." (PMID 30540250, 2018). "In the setting of cancer, beyond platelet activity, the role of RGS7 is not clear." (PMID 40425987, 2025).
RGS7 also shares sentences with these, for which no sentence is quoted: Alzheimer disease (2 papers); autism (2); schizophrenia (2); adenocarcinoma (1); alcohol dependence (1); autism spectrum disorder (1); benign neoplasm (1); bipolar disorder (1); diabetes (1); Hepatic steatosis (1); neuroblastoma (1); non-small cell lung carcinoma (1); panic disorder (1); Parkinson disease (1); psychiatric disorder (1); squamous cell carcinoma (1); substance abuse (1); Uterine leiomyoma (1); Venous thrombosis (1).